METTL3 (methyltransferase 3, N6-adenosine-methyltransferase complex catalytic subunit)
Diseases named in the same sentence as METTL3 in open-access papers (continued):
Sharing a sentence is not in itself a finding about the gene and the disease.
glioma (continued). "Recently, the Wang group demonstrated that METTL3 promoted the malignant progression of IDH-wt gliomas while upregulating the expression of the lncRNA MALAT1 by enhancing its stability via m6 A modification." (PMID 40382536, 2025). "To elucidate the mechanism by which METTL3 inhibits autophagy in gliomas via EIF3J-AS1, we performed RNA-seq to identify target genes regulated by METTL3." (PMID 41390674, 2025). "It is worth noting that the upregulation of METTL3 and various m6A methylation levels significantly promote glioma cell resistance to TMZ." (PMID 40469294, 2025). "Our study underscores the pivotal role of METTL3 in glioma tumorigenesis and provides new insights into its post-translational regulation at the subcellular level." (PMID 41321637, 2025). "Studies have reported that high METTL3 expression in gliomas increases their resistance to antiangiogenic drugs." (PMID 40469294, 2025). "Methylated RNA immunoprecipitation (MeRIP) and bioinformatics analyses confirmed m6A modification of EIF3J-AS1, which correlates positively with the m6A methyltransferase METTL3 in glioma tissues." (PMID 41390674, 2025). "In our study, we found that METTL3 is significantly overexpressed in high grade glioma, METTL3 knockout inhibited the malignancy and tumorigenicity of GBM cells." (PMID 41321637, 2025). "As one of the most significant m6A writers, METTL3 has great potential for the development of drugs to treat gliomas." (PMID 40469294, 2025). "In the majority of cases, METTL3 is known to promote glioma development, and studies have reported that its overexpression enhances the formation of VM in gliomas, thereby increasing glioma resistance to treatment." (PMID 40469294, 2025). "Visvanathan and colleagues demonstrated that the majority of noncoding lincRNAs were upregulated (opposite to what was observed for mRNAs) under induced depletion of METTL3 in glioma stem cells." (PMID 40382536, 2025). "Our findings highlight that METTL3 undergoes distinct post-translational modifications based on its subcellular localization, providing new insights into the spatial regulation of METTL3 in gliomas." (PMID 41321637, 2025). "Compared to the miR-101 overexpression group, glioma cells co-expressing miR-101 and METTL3 exhibited enhanced proliferation, restored p62 protein levels, decreased LC3II expression, and suppressed autophagic flux." (PMID 41390674, 2025). "Targeted METTL3 inhibition has been shown to suppress mitophagy in glioma cells, thereby facilitating GBM stem cell proliferation and self-renewal and counteracting temozolomide-induced drug resistance." (PMID 41390674, 2025). "In gliomas, H3K18la activates methyltransferase like protein 3 (METTL3) transcription and mediates RNA m6A modifications to foster immunosuppression in tumor-infiltrating myeloid cells." (PMID 40806283, 2025). "To verify the clinical implications of METTL3 in glioma, we performed immunohistochemistry (IHC) staining to assess METTL3 expression in a glioma tissue microarray (TMA) cohort, with specimens collected from our institution." (PMID 41321637, 2025). "To investigate the correlation between METTL3 and USP25, we analyzed the protein levels of USP25 and METTL3 in a broad panel of cancer cell lines and 37 clinical glioma samples, along with 11 brain tissues from patients with non-tumor." (PMID 41321637, 2025). "In this study, we will explore the mechanisms by which miR-101 and METTL3 regulate the expression of EIF3J-AS in glioma and its role in autophagy." (PMID 41390674, 2025). "In this study, we demonstrated that miR-101 facilitated autophagy by targeting METTL3 in glioma cells." (PMID 41390674, 2025). "Collectively, findings regarding the roles of METTL3 in glioma across different studies are inconsistent." (PMID 38398118, 2024).
glioma (continued). "IGF2BP3 downregulated the expression of both m6A-associated writers (METTL3, METTL14) and erasers (FTO, ALKBH5), with a specific focus on FTO due to its more pronounced effect in both U87MG and GL261 glioma cell lines." (PMID 38167409, 2024). "A significant up-regulation of METTL3 was observed in glioma compared to normal brain tissues, and was significantly higher in GBMs than in LGGs." (PMID 38405130, 2024). "In vivo and in vitro, 1C-containing Jumonji domains promote M1 macrophage polarization and inhibit the development of glioma xenografts via the miR-302a/METTL3/SOCS2 axis." (PMID 38523627, 2024). "Up-regulation of METTL3 stimulated cell proliferation and migration, while inhibition of METTL3 expression suppressed cell proliferation in glioma cells." (PMID 38405130, 2024). "Elevated METTL3 levels in glioma contribute to VM through targeting HOXA transcript antisense RNA myeloid-specific 1 (HOTAIRM1)." (PMID 39098905, 2024). "METTL3-dependent m6A modification imparts HOTAIRM1 stability in glioma cells, and m6A-modified HOTAIRM1 transcript plays a vital role in the promotion of VM formation." (PMID 39691597, 2024). "In order to investigate the mechanism underlying METTL3 and LINC00475-S-induced mitochondrial fission in glioma cells, we performed RNA sequencing (RNA-seq)." (PMID 38405130, 2024). "This study validated that METTL3 promoted mitochondrial fission in glioma cells, thus fostering glioma progression." (PMID 38405130, 2024). "METTL3 sustains the stemness of glioma stem cells and confers radiotherapy resistance by promoting m6A methylation on LINC00839." (PMID 38405130, 2024). "Further investigation with more standardized protocols or larger sample sizes is needed to reconcile these discrepancies and provide a more comprehensive understanding of METTL3’s involvement in glioma." (PMID 38398118, 2024). "To elucidate the mechanism by which METTL3 facilitates LINC00475 splicing in gliomas, we employed pulldown-LC/MS (liquid chromatography/mass spectrometry) to screen proteins that directly interact with LINC00475." (PMID 38405130, 2024). "HOTAIRM1 can positively regulate IGFBP2 expression, and IGFBP2 binds with HOTAIRM1 via METTL3-mediated m6A binding-domains and increases its stability and expression in glioma tissues and cells." (PMID 39691597, 2024). "In fact, METTL3 and ALKBH5 are supposed to have opposite roles in regulating cell proliferation of glioma because METTL3 increases m6A level but ALKBH5 reduces m6A levels." (PMID 38398118, 2024). "In gliomas, the expression levels of METTL3, ALKBH5, YTHDF2, and IGF2BP3 were found to be elevated compared to normal brain tissues." (PMID 38398118, 2024). "Collectively, this study elaborated a novel function of PDGF, wherein it governs the transcription of METTL3, leading to consequential changes in m6A levels in glioma." (PMID 38398118, 2024). "Down-regulation of METTL3 enhances the ability of the PI3K/AKT pathway to promote glioma migration and invasion." (PMID 39289775, 2024). "In gliomas, the expression of METTL3 was significantly downregulated in tumor tissues compared to adjacent normal tissues." (PMID 39289775, 2024). "METTL3 is involved in the methylation of non-coding RNAs, including lncRNAs and circRNAs, which are critical in glioma initiation and progression." (PMID 38474421, 2024). "By using GSCs and established glioma cell lines, the authors found that METTL3 is essential for maintaining GSCs and reprogramming of the established glioma cell lines." (PMID 38398118, 2024). "In glioma, IGFBP2 is closely associated with METTL3-mediated HOTAIRM1 via its m6A binding-domains and positively regulated by HOTAIRM1, thus promoting VM." (PMID 39691597, 2024). "A more recent study has shown, using both glioma cell lines and mouse models, that METTL3 methylates ADAR1 mRNA which, mediated by YTHDF1, led to its increased expression at the protein level." (PMID 37444417, 2023).
glioma (continued). "METTL3-mediated m6A modification plays a critical role in the maintenance of glioma stem-like cells (GSCs) and glioma cell dedifferentiation." (PMID 37264402, 2023). "Mechanistically, HOTAIRM1 promotes VM formation mediated by METTL3 in glioma progression via regulating IGFBP2 expression." (PMID 38012763, 2023). "Further analysis indicated that METTL3 depletion partially rescued the impact of HOTAIRM1 on glioma cell malignancy and VM formation." (PMID 38012763, 2023). "Results revealed that glioma cell proliferation was significantly promoted when METTL3 was overexpressed, and glioma cell proliferation capacity was reduced when METTL3 was silenced relative to the control." (PMID 38012763, 2023). "Collectively, these results suggest that HOTAIRM1 silencing partially counteracts METTL3 mediated glioma cell malignancy and VM formation capacity." (PMID 38012763, 2023). "Chang and colleagues confirmed that the expression of METTL3 was positively correlated to an increased malignant grade of IDH-WT glioma." (PMID 38072944, 2023). "Mechanistically, METTL3 was highly expressed in glioma tissues and cells and was bound with HOTAIRM1 which stabilized HOTAIRM1 expression." (PMID 38012763, 2023). "We then investigated the effects of METTL3 on glioma cell malignancy and evaluated METTL3-HOTAIRM1 regulatory pattern in glioma cellular processes by conducting loss-of-function experiments." (PMID 38012763, 2023). "The GEPIA2 database showed that METTL3 had the highest positive correlation with LINC01003 in glioma tissues." (PMID 37270527, 2023). "For example, an in vitro study demonstrated that METTL3 can activate the Notch pathway and facilitate glioma development by regulating the pathway targets NOTCH3, delta-like protein 3(DLL3), and HES1." (PMID 37189411, 2023). "METTL3 (termed “writers”), the key component of the m6A methyltransferase complex, has been reported to regulate the malignant progression of glioma." (PMID 37270527, 2023). "Other studies have indicated that METTL3 is downregulated in glioma tissues and regulates U251 cell proliferation and apoptosis by targeting COL4A1 and HSP9, potential therapeutic targets of glioma." (PMID 37189411, 2023). "Further analysis found that METTL3 presented up-regulation in low and high-grade glioma tissue compared to the control and its expression was higher in high-grade glioma tissue relative to that in low-grade." (PMID 38012763, 2023). "Studies show that the overall m6A modification and METTL3 level in GBM are high compared with differentiated glioma cells (DGCs)." (PMID 37522921, 2023). "Rescue assays demonstrated that METTL3 silencing counteracted the impact of HOTAIRM1 on glioma cell malignancy and VM formation capacity." (PMID 38012763, 2023). "One study noted that high METTL3 expression impeded glioma growth in vitro and in vivo, mainly attributed to the maintenance of intracellular mRNA m6A levels by METTL3." (PMID 37344779, 2023). "Meanwhile, another study in glioma stem-like cells (GSCs) also indicated that METTL3 expression is downregulated." (PMID 37189411, 2023). "Multiple papers have reported that the m6A writer METTL3 is upregulated in glioma stem cells (GSCs) and contributes to tumorigenesis." (PMID 37444417, 2023). "Subsequently, qRT-PCR, western blotting and immunohistochemical staining were performed to measure the expression changes of METTL3 in glioma cells and tissues, respectively." (PMID 38012763, 2023). "The RNA m6A methyltransferase METTL3 was shown to epigenetically mediate the upregulation of LINC01003 in glioma." (PMID 37270527, 2023). "In summary, our data demonstrate that HOTAIRM1 facilitates METTL3-mediated VM formation in glioma via up-regulating IGFBP2 expression (graphical abstract)." (PMID 38012763, 2023). "The expression of METTL3 is increased in glioma stem-like cells (GSCs), which plays an important role in the maintenance and radioresistance of GSCs by regulating m6A modification of SOX2 mRNA." (PMID 37714846, 2023).
glioma (continued). "Mettl3 KD has been shown to enhance cellular proliferation, motility, and invasion of glioma cells in vitro, and glioma development in vivo." (PMID 38072944, 2023). "It was also found that YTHDF2 promotes the decay of UBXN1 mRNA through recognition of METTL3-mediated m6A modifications, thereby activating NF-κB and promoting the malignant progression of glioma." (PMID 35937991, 2022). "The m6A level in glioma tissues and cells was consistent with the trend of METTL3 expression (p < 0.01)." (PMID 35474040, 2022). "This study probed into the effect of METTL3-mediated m6A methylation of circDLC1 on the malignant proliferation of glioma cells and the downstream ceRNA mechanism of circDLC1, hoping to shed light on glioma treatment." (PMID 35474040, 2022). "After METTL3 pcDNA 3.1 (pc-METTL3) was transfected into glioma cells (p < 0.05), the m6A level in cells, circDLC1 expression, and m6A level of circDLC1 were also increased (p < 0.01)." (PMID 35474040, 2022). "A xenograft tumor model was established in nude mice to verify the effect of METTL3-mediated circDLC1 on glioma in vivo." (PMID 35474040, 2022). "METTL3-mediated m6A modification played a crucial role in glioma stem-like cell maintenance and radioresistance." (PMID 35064112, 2022). "Further research suggested that SOX2 stabilized by METTL3 with recruitment of HuR was related to the maintenance and radiation resistance of glioma stem-like cells." (PMID 36008936, 2022). "To verify the role of METTL3 in the regulation of glioma cells by circDLC1, we transfected three METTL3 siRNAs (si-METTL3) into LN229 cells respectively (p < 0.05) and selected si-METTL3#2 with the best transfection efficiency for subsequent experiments." (PMID 35474040, 2022). "Briefly, METTL3 overexpression annulled the promoting effect of circDLC1 silencing on glioma cell proliferation." (PMID 35474040, 2022). "METTL3 overexpression repressed the malignant proliferation of glioma via circDLC1/miR-671-5p/CTNNBIP1 in vivo." (PMID 35474040, 2022). "Mechanically, METTL3-mediated m6A modification enhanced circDLC1 stability and upregulated circDLC1 expression in glioma." (PMID 35474040, 2022). "This study first reported the mechanism of METTL3-mediated m6A modification of circDLC1 on the malignant proliferation of glioma cells, shedding light on glioma treatment." (PMID 35836125, 2022). "Briefly, METTL3 suppressed glioma cell malignant proliferation via the circDLC1/miR-671-5p/CTNNBIP1 axis in vivo." (PMID 35474040, 2022). "The m6A writer METTL3 is elevated in glioma stem-like cells (GSCs), where it mediates GSC maintenance and dedifferentiation by regulating SOX2 mRNA stability." (PMID 35717510, 2022). "Later studies revealed that METTL3 can inhibit the proliferation, migration, and invasion of glioma cells and induce their apoptosis by inhibiting the protein phosphorylation level in the PI3K/Akt/mTOR pathway." (PMID 35682599, 2022). "Our results exhibited that the m6A level, METTL3 expression, and m6A level of circDLC1 were reduced in glioma tissues and cells." (PMID 35474040, 2022). "In glioma stem-like cells, METTL3 and METTL14 were also shown to suppress cell differentiation, while WTAP and ALKBH5 promote cell proliferation, self-renewal, and tumorigenicity." (PMID 36293529, 2022). "An example is circDCL1, whereby upregulation of this circRNA through METTL3-mediated m6A modification repressed the malignant proliferation of glioma cells." (PMID 36425564, 2022). "The expression of METTL3, significantly elevated in glioma stem-like cells (GSCs) and attenuated during differentiation, is the most important m6A writer." (PMID 35625706, 2022). "For example, METTL3 plays essential roles in preserving glioma stem-like cells and radio-resistance by stabilizing the mRNA of m6A-modified SOX2 via HuR." (PMID 36614956, 2022). "Briefly, METTL3 suppressed the glioma cell proliferation via the circDLC1/miR-671-5p/CTNNBIP1 axis in vivo." (PMID 35474040, 2022).
glioma (continued). "In contrast, in another publication, it has been shown that METTL3 as an oncogene is clearly more abundant in gliomas." (PMID 35462896, 2022). "The recent literature has found that METTL3 can promote the malignant progression of glioma by regulating the stability of MALAT1 and activating NF-κB." (PMID 36114893, 2022). "As for the interplay between Notch and m6A, a recent study revealed that METTL3 (methyltransferase like 3), a subunit of the N6-methyltransferase complex, is able to methylate several Notch transcripts and potentiate Notch activity in glioma stem-like cells." (PMID 33966637, 2021). "Our results suggested that IGF2BP2, KIAA1429, METTL16, and METTL3, as well as 208 targets are involved in the occurrence of glioma, GBM, and LGG." (PMID 34589481, 2021). "Our analysis suggested that Notch signaling pathway (including key genes METTL3, DLL3, HES1, and NOTCH3) closely implicated with tumorigenesis and cancer development was found to be involved in glioma." (PMID 34589481, 2021). "JMJD1C promoted M1 macrophage polarization and suppressed the growth of glioma xenografts through the miR‐302a/METTL3/SOCS2 axis both in vivo and in vitro." (PMID 34586733, 2021). "Together, these findings showed that YTHDF2 can accelerate UBXN1 mRNA decay in gliomas via METTL3-mediated m6A modification." (PMID 34246306, 2021). "In summary, we have demonstrated that METTL3 promotes the TMZ resistance of glioma cells by increasing MGMT and ANPG in an m6A-dependent manner." (PMID 34336690, 2021). "Collectively, METTL3 acts as a critical promoter of TMZ resistance in glioma and extends the current understanding of m6A related signaling, thereby providing new insights into the field of glioma treatment." (PMID 34336690, 2021). "Some studies have suggested that overexpression of METTL3 profoundly inhibited the proliferation, tumorigenicity and migration ability of glioma, breast cancer or bladder cancer cells by altering the mRNA expression of genes or proteins." (PMID 33431045, 2021). "Mechanistically, YTHDF2 accelerates UBXN1 mRNA decay in gliomas by recognizing the m6A modification mediated by METTL3." (PMID 34246306, 2021). "METTL3 regulates the proliferation, migration, and invasion of glioma cells by inhibiting PI3K/Akt signaling pathway." (PMID 34212046, 2021). "METTL3 is a widely recognized “writer of m6A, and its expression determines the level of m6A modification of RNAs in glioma." (PMID 34246306, 2021). "In conclusion, JMJD1C promotes M1 macrophage polarization and inhibits glioma development through the miR‐302a/METTL3/SOCS2 axis." (PMID 34586733, 2021). "Together, these data indicate that there are METTL3-mediated m6A modification sites on UBXN1 mRNA that have the potential to be recognized by YTHDF2 in glioma cells." (PMID 34246306, 2021). "Elevated METTL3 mRNA expression was observed in IDH-mutant gliomas in both cohorts, consistent with our recent report." (PMID 34246306, 2021). "To further validate the influence of METTL3 in Notch signaling pathway and glioma occurrence, we knocked down METTL3 in two GBM cell lines." (PMID 34589481, 2021). "In another example, METTL3 exhibited an inhibitory role in the proliferation, tumorigenicity and migration ability in glioma cells, which had a paradoxical effect." (PMID 33431045, 2021). "We and others have reported that m6A ‘writers,’ particularly METTL3, also play important roles in the tumorigenesis and malignant progression of glioma." (PMID 34246306, 2021). "In and glioma stem-like cells, METTL3 mediated SOX2 expression through an m6A-dependent mechanism to promote RNA stability and then increase stem cell frequency." (PMID 34315512, 2021). "Paradoxically, other studies have shown that by silencing METTL3 or WTAP (only in glioma), similar cell growth and aggressiveness inhibition was achieved." (PMID 33431045, 2021).